MIR647 (microRNA 647)
Synonyms: hsa-mir-647; MIRN647
Gene: MicroRNA gene on chromosome 20 (63,942,631 to 63,942,726, reverse strand). Ensembl gene ENSG00000207554.
Diseases named in the same sentence as MIR647 in open-access papers:
MIR647 is named in the same sentence as 3 diseases in open-access papers, as found by Europe PMC text mining. Sharing a sentence is not in itself a finding about the gene and the disease.
MIR647 shares sentences with these, for which no sentence is quoted: lung adenocarcinoma (1 paper); oral squamous cell carcinoma (1); prostate carcinoma (1).